Y_RNA (Y RNA )
Gene: Miscellaneous RNA gene on chromosome 14 (22,852,616 to 22,852,728, reverse strand). Ensembl gene ENSG00000212335.
Homologues: Orthologues: chimpanzee Y_RNA (100% identical), macaque Y_RNA (95% identical). Paralogues in human: Y_RNA (89% identical), RNY1 (88% identical), Y_RNA (88% identical), Y_RNA (87% identical), RNY1P11 (86% identical), Y_RNA (86% identical), Y_RNA (85% identical), RNY1P7 (84% identical), Y_RNA (84% identical), RNY1P8 (83% identical), Y_RNA (83% identical), Y_RNA (82% identical), and 95 more.